AHR (aryl hydrocarbon receptor)
Diseases named in the same sentence as AHR in open-access papers (continued):
Sharing a sentence is not in itself a finding about the gene and the disease.
urothelial carcinoma (4 papers, 2017 to 2022). A malignant neoplasm derived from the transitional epithelium of the urinary tract (urinary bladder, ureter, urethra, or renal pelvis). "GRα, AhR, and ERα ligands may be beneficial in the treatment of uroepithelial carcinomas." (PMID 27690298, 2017).
acute respiratory distress syndrome (3 papers, 2023 to 2024). Progressive and life-threatening pulmonary distress in the absence of an underlying pulmonary condition, usually following major trauma or surgery. "This is in line with the antiviral activity of AhR agonists against Influenza A virus and the protection against Acute Respiratory Distress Syndrome." (PMID 39057395, 2024). "In the current study, we investigated the role of AhR and the ability of I3C to attenuate LPS-induced Acute Respiratory Distress Syndrome (ARDS)." (PMID 38596679, 2024).
airway allergy (3 papers, 2021 to 2024). "In a model of ovalbumin-induced airway allergy, AhR-deficient mice developed more severe allergic responses due to the increased ability of AhR-deficient T cells to proliferate and the higher activation of AhR-deficient lung DC." (PMID 37190854, 2023). "Our findings were supported by some other studies showing that BaP can directly induce AhR activation that contributes to the pro-inflammatory response in respiratory allergy through enhancing IL-33 expression and eosinophil infiltration." (PMID 33936062, 2021). "This protein also reduces AHR, lung inflammation, and TH2 immune responses in different mouse models of airway allergy." (PMID 39409176, 2024).
amyotrophic lateral sclerosis (3 papers, 2018 to 2024). Amyotrophic lateral sclerosis (ALS) is a neurodegenerative disease characterized by progressive muscular paralysis reflecting degeneration of motor neurons in the primary motor cortex, corticospinal tracts, brainstem and spinal cord. "The observed effects were abrogated by AhR antagonists, implying that exposure to the environmental toxic substances that activate AhR may be a risk factor for the onset or progression of amyotrophic lateral sclerosis." (PMID 35743162, 2022). "Finally, the AhR has been identified as a regulator of TDP-43 expression, a biomarker of the development of amyotrophic lateral sclerosis (ALS), suggesting for the first time that a potential link exists between environmental ligands and the development of these neurodegenerative diseases." (PMID 30149528, 2018).
Atrophy (3 papers, 2010 to 2017). Any weakening or degeneration, especially through lack of use. "We found that AhR is normally expressed at low levels in the prostatic epithelium basal cells (cytoplasmic and nuclear staining) and is substantially upregulated in areas of proliferative inflammatory atrophy (PIA), considered a precursor lesion to cancer." (PMID 20140206, 2010). "AHR is involved in the regulation of biological responses to planar aromatic hydrocarbons; UBE2L6 targets abnormal or short-lived proteins for degradation; and PAFAH1B3 functions in brain development and is associated with mental retardation, ataxia, and atrophy of the brain." (PMID 28178176, 2017).
breast adenocarcinoma (3 papers, 2018 to 2021). "Further studies showed that G protein-coupled receptor 30 (GPR30) agonist G-1 increased AhR signaling by inhibition of tubulin assembly and cell cycle arrest in human breast adenocarcinoma (MCF-7) cells." (PMID 34342853, 2021).
cerebral artery occlusion (3 papers, 2020 to 2024). "Involvement of AhR in acute ischemic stroke has been demonstrated by pharmacological and genetic approaches to AhR loss of function in a mouse model of middle cerebral artery occlusion, where ischemic injury upregulates the AhR protein and its transcriptional activity in neurons." (PMID 39000041, 2024). "We previously reported that AhR, which is a receptor for PAHs to induce the upregulation of inflammatory molecules, in microglia is involved in neuroinflammation and subsequent brain damage after middle cerebral artery occlusion." (PMID 36797786, 2023).
Chagas disease (3 papers, 2016 to 2023). A parasitic infection caused by Trypanosoma cruzi. "Cardiac patients exhibited higher mRNA expression of IFN-γ, TNF-α and lower mRNA expression of IL-10, Foxp3, AHR, and GATA-3 than those with the indeterminate clinical form of Chagas disease." (PMID 27115869, 2016).
choriocarcinoma (3 papers, 2020 to 2025). An aggressive malignant tumor arising from trophoblastic cells. "All these results suggested that VEGF-B mediated choriocarcinoma cell migration and invasion by targeting AhR." (PMID 35773697, 2022). "Due to the limited data regarding choriocarcinoma, the GEO datasets were used to conduct bioinformatics analysis on different cell lines intervened by AhR agonists, AhR antagonists, or AhR knockout." (PMID 35773697, 2022). "For example, in head and neck carcinoma, lung carcinoma, and choriocarcinoma cell lines, the AHR regulates expression of an ABC transporter, ABCG2, which contributes to chemoresistance by exporting drugs out of the cell against a concentration gradient." (PMID 33396563, 2020). "It is probable for the VEGF-B/AhR axis mentioned in the present study to be functional in preventing the migration and invasion of choriocarcinoma cells, which may be a possible therapeutic strategy for choriocarcinoma." (PMID 35773697, 2022). "AHR expression is elevated and nuclear in choriocarcinoma, TNBC, and oral squamous cell CSCs." (PMID 33396563, 2020). "However, the mechanism of AhR in choriocarcinoma metastasis is yet to be fully elucidated." (PMID 35773697, 2022).
chronic rhinosinusitis (3 papers, 2021 to 2025). Chronic form of sinusitis. "Moreover, the AhR is a pivotal effector in many pathological processes, such as cancer, intestinal inflammation, hepatic steatosis, chronic rhinosinusitis, and atopic dermatitis." (PMID 34746229, 2021). "Moreover, the authors exhibited that miR-124 could modulate cellular inflammatory response through negatively regulating AhR expression and inflammatory cytokine (TNF-α) that is critical to the development of inflammatory response in chronic rhinosinusitis (CRS) with nasal polyps (CRSwNPs)." (PMID 34746229, 2021).
colorectal tumor (3 papers, 2022 to 2024). "Studies with AhR KO mice documented a higher colorectal tumor incidence in the AhR-deficient animals than in their wild-type counterparts." (PMID 36077780, 2022).
congenital nystagmus (3 papers, 2017 to 2025). Nystagmus present at birth or caused by lesions sustained in utero or at the time of birth. "Intriguingly, loss-of-function mutations in AHR genes are considered the genetic etiology of congenital nystagmus in both humans and mice, suggesting a possible role of AHR in nervous system development across species." (PMID 40711040, 2025). "AHR−/− mice demonstrated congenital nystagmus, which suggests that AHR may play an important role in the pathogenesis of congenital nystagmus and related CNS pathologies." (PMID 30513921, 2018). "Therefore, AHR appears to play crucial roles in multiple CNS diseases, including MDD, MS, and congenital nystagmus, and it is also important for the gut-brain axis, which may contribute to these and other CNS diseases." (PMID 30513921, 2018). "AHR−/− mice demonstrated the dysregulation of myelin structure, increased pro-inflammatory cytokine gene expression, and STAT1 target gene dysregulation, all of which may contribute to congenital nystagmus." (PMID 30513921, 2018).
dengue (3 papers, 2017 to 2021). "For the AHRR gene, the protective phenotype also has a lower expression profile, and as this protein will inhibit AHR protein, these individuals will have a higher expression of AHR, which is opposite to the expression pattern observed in the dengue patients transcriptome." (PMID 29447178, 2018). "We thus sought to determine whether HELZ2 interacts with a nuclear receptor known to regulate immune response and lipid metabolism, AHR, and identified HELZ2:AHR interactions via co-immunoprecipitation, found that AHR is a dengue IEG, and that an AHR ligand, FICZ, exhibits anti-dengue activity." (PMID 28265266, 2017).
diabetic retinopathy (3 papers, 2021 to 2025). "Omeprazole-induced AhR activation reduced oxidative damage in peripheral blood mononuclear cells and demonstrated protective effects against oxidative stress and diabetic retinopathy." (PMID 41440753, 2025). "Omeprazole-induced AhR activation can help prevent diabetic retinopathy; however, long-term exposure may lead to metabolic alterations, including increased insulin and blood glucose levels." (PMID 41440753, 2025). "In our current study, we examined an aryl hydrocarbon receptor (AhR) agonist, VAF347, that can inhibit Th17 cell differentiation as another potentially novel therapeutic for diabetic retinopathy." (PMID 33919327, 2021). "Hence, these results suggest that the AhR agonist VAF347 would be a good therapeutic candidate for non-proliferative diabetic retinopathy." (PMID 33919327, 2021). "In the current study, we examined the efficacy of an AhR agonist, VAF347, as a potential therapeutic for the onset of non-proliferative diabetic retinopathy in streptozotocin (STZ)-induced diabetic C57BL/6 mice." (PMID 33919327, 2021). "Taken together, we postulated that AhR agonist VAF347 will halt Th17 cell differentiation and IL-17A production, which will ameliorate retinal inflammation, and halt the onset of non-proliferative diabetic retinopathy in STZ-diabetic mice." (PMID 33919327, 2021).
diffuse large B-cell lymphoma (3 papers, 2016 to 2024). "Suppression of AHR by hypermethylation has also been described for different cancer cell lines including the osteosarcoma cell lines U2OS and 143B, the diffuse large B-cell lymphoma cell lines U-2932 R2 and OCI-LY19, the chronic myeloid leukemia cell line K562 and the ALL cell lines Jurkat and REH." (PMID 37696456, 2023). "A recent report showed that AhR and its activating enzymes, IDO1 and tryptophan 2,3- dioxygenase (TDO), were highly expressed in diffuse large B-cell lymphoma (DLBCL) patient samples and were inversely correlated with patient survival." (PMID 38807762, 2024).
dilated cardiomyopathy (3 papers, 2023 to 2025). Cardiomyopathy which is characterized by dilation and contractile dysfunction of the left and right ventricles. "Furthermore, Studies have demonstrated that the activation of Th22 cells in dilated cardiomyopathy patients is linked to a heightened expression of the aryl hydrocarbon receptor (AHR) in the peripheral blood, potentially playing a role in the pathogenesis of DCM." (PMID 37512058, 2023).
embryonic carcinoma (3 papers, 2018 to 2022). "Whereas the associated AhR heterodimerization partner ARNT2, as well as ARNT1, were up-regulated after human motor neuron differentiation from hiPSCs, only ARNT2 was up-regulated in neurons differentiated from murine embryonic carcinoma cells P19." (PMID 35890127, 2022).
encephalomyelitis (3 papers, 2020 to 2024). Inflammation of the brain and the spinal cord. "In an encephalomyelitis mouse model, supplementation with Trp or Trp-derived aryl hydrocarbon receptor (AhR) agonists increased IFN-suppressive effects in an AhR-dependent manner and reduced central nervous system inflammation." (PMID 38250060, 2023). "Previous research showed that AhR activation by 6-formylindolo[3,2-b] carbazole (FICZ) boosted Th17 cell differentiation and aggravated encephalomyelitis." (PMID 33082710, 2020).
endotoxemia (3 papers, 2017 to 2025). "Persistent, high-affinity AhR agonists such as TCDD represent a clear risk for epithelial barrier dysfunction and systemic endotoxemia, whereas controlled activation by dietary or pharmacological ligands may enhance barrier resilience and mucosal immunity." (PMID 41304545, 2025). "Interestingly, AHR-KO mice exhibited the same susceptibility to LPS than TDO-KO mice, suggesting an immunosuppressive effect of tryptophan catabolites against endotoxemia mediated by AHR." (PMID 36188218, 2022).
Ewing sarcoma (3 papers, 2020 to 2025). A small round cell tumor that lacks morphologic, immunohistochemical, and electron microscopic evidence of neuroectodermal differentiation. "In additional models including Ewing sarcoma, however, autocrine AHR activation was repressed by oncogenic signaling, suggesting tumor-suppressive activity." (PMID 33214553, 2020).
Glomerular sclerosis (3 papers, 2020 to 2024). Accumulation of scar tissue within the glomerulus. "The activation of AHR can cause progressive damage to glomerular and tubular cells, leading to glomerulosclerosis and tubulointerstitial fibrosis, thus exacerbating CKD." (PMID 37362429, 2023). "Accumulated IS during renal function decline can stimulate glomerular sclerosis and renal tubular dysfunction via AhR and, consequently, CKD progression." (PMID 32867359, 2020).
graft versus host disease (3 papers, 2011 to 2024). An immune system disorder that occurs after allogeneic hematopoietic stem cell transplant and is a reaction of donor immune cells against host tissues. "Unlike TCDD, 10-Cl-BBQ is rapidly metabolized yet is capable of inducing AhR-dependent Tregs and suppressing the murine graft versus host disease (GVHD) in an AhR-dependent manner." (PMID 24586378, 2014). "For instance, it was shown that 3-IAld could limit graft-versus-host disease (GvHD) by activating type I IFN signaling, consistent with the notion that not only the diversity of the ligands, but also the context in which AhR is activated may direct downstream signaling pathways." (PMID 39057395, 2024).
heart malformations (3 papers, 2013 to 2023). "PAH exposure has also been linked to an increase in congenital heart defects, and AHR agonists have been repeatedly shown to cause heart malformations in animal models." (PMID 37755789, 2023). "For example, extractable organic matter (EOM) from PM2.5 may cause heart malformations and decreased heart rates in zebrafish embryos through the AhR, and these heart defects appear to be counteracted in embryos co-exposed to EOM and an AhR antagonist." (PMID 28754128, 2017). "Zebrafish embryos exposed during the temporal window of epicardium development to the aryl hydrocarbon receptor (AHR) agonist 2,3,7,8-tetrachlorodibenzo-p-dioxin (TCDD) exhibit severe heart malformations." (PMID 25232532, 2013).
hepatoblastoma (3 papers, 2013 to 2022). Hepatoblastoma (HB) is a malignant hepatic tumor and is the most common pediatric liver cancer. "Enhanced expression of AhR protein was also observed in NIH3T3 mouse fibroblast cells, 1.8-fold after 6-h exposure, and in WI38 human diploid cells and HepG2 human hepatoblastoma cells, 2.1-fold and 1.5-fold after 2-h exposure, respectively." (PMID 33723743, 2022). "In conclusion, the AhR pathway, which involves ATF4, induces VEGF expression in glucose-deprived human hepatoblastoma HepG2 cells." (PMID 24330582, 2013).
hyperandrogenism (3 papers, 2022 to 2025). Excessive secretion of androgens from the adrenal glands or gonads. "In women with PCOS, a correlation between elevated levels of AhR, ARNT, CYP1A1, and CYP1B1 genes and clinical hyperandrogenism, follicular fluid testosterone levels, and disturbed folliculogenesis was observed." (PMID 37572199, 2023).
idiopathic pneumonia syndrome (3 papers, 2020 to 2023). "For example, kynurenine induced clot weights in a mouse model for venous thrombogenicity, whereas in a model for idiopathic pneumonia syndrome kynurenine inhibited lung damage and the AhR antagonist CH223191 inhibited kynurenine-induced responses." (PMID 32932962, 2020). "In a lung model of pulmonary inflammation known as idiopathic pneumonia syndrome (IPS), an HDAC inhibitor induced L-kynurenine and suppressed IL-17 and IL-6 expression, and these damage-related responses were reversed after treatment with the AhR antagonist CH223191." (PMID 32932962, 2020).
Immunodeficiency (3 papers, 2015 to 2022). Failure of the immune system to protect the body adequately from infection, due to the absence or insufficiency of some component process or substance. "The persistence of immune deficiency throughout life suggests that the cellular target of AHR activation is a fetal hematopoietic progenitor or stem cell." (PMID 26495820, 2016). "The microbial metabolites of phenylalanine and tyrosine, which engage the aryl hydrocarbon receptor (AhR) and promote interleukin (IL)-22 secretion, and contribute to local immunization, were reported to be reduced in patients who developed ACLF, which manifested a relative immunodeficiency." (PMID 36059949, 2022).
intestinal cancer (3 papers, 2020 to 2025). "With the help of organoid modeling, our group also demonstrated that AhR significantly enhances stemness and migration of intestinal cancer cells by promoting the activation of the Wnt/β-catenin signaling pathway in intestinal cancer cells." (PMID 40406485, 2025). "Clearly, AhR-dependent control of the Wnt/β-catenin signaling pathway represents an important mechanism through which the receptor promotes tumor suppression in at least liver and intestinal cancers." (PMID 37106727, 2023).
invasive ductal carcinoma (3 papers, 2018 to 2022). "In a study of 90 patients with invasive ductal breast carcinoma, AhR was expressed in the cytoplasm with higher expression than in normal duct epithelium." (PMID 30813617, 2019). "Saito (2014) previously reported that AhR status was inversely correlated with the histological grade of invasive ductal carcinoma." (PMID 29320557, 2018). "There were some differences in the nuclear and extranuclear distribution of AhR protein in non-pathological breast ductal epithelial cells and invasive ductal carcinoma and AhR overexpression was associated with better prognosis of ER-negative and ER-positive invasive ductal carcinoma patients." (PMID 36428667, 2022).
kidney inflammation (3 papers, 2018 to 2024). "IS, a uremic toxin generated by the gut microbiota fermenting proteins, translocates into the nucleus after binding to the aryl hydrocarbon receptor (AhR), which contributes to kidney inflammation and fibrosis." (PMID 39717782, 2024).
Leber congenital amaurosis (3 papers, 2019 to 2023). Leber congenital amaurosis (LCA) is a retinal dystrophy defined by blindness and responses to electrophysiological stimulation (Ganzfeld electroretinogram (ERG)) below threshold, associated with severe visual impairment within the first year of life. "A congenital form of RP, called Leber Congenital Amaurosis (LCA), is also associated with the AHR, indirectly through aryl hydrocarbon interacting protein-like 1 protein (AIPL1)." (PMID 32947781, 2020). "Aryl hydrocarbon receptor (AhR)-interacting protein-like 1 (AIPL1) was first discovered in association with Leber congenital amaurosis (LCA)." (PMID 31344897, 2019). "The list included genes associated with different forms of Leber congenital amaurosis, involved in disruptions in phototransduction (AIPL1), retinoid cycle (RDH12, RPE65), and transport across the photoreceptor connecting cilium (LCA5), as well as genes evidently interacting with AIPL1 (NUB1, AHR)." (PMID 38203368, 2023).
left ventricular hypertrophy (3 papers, 2016 to 2024). Enlargement of the LEFT VENTRICLE of the heart. "Recent studies have shown that increased plasma kynurenine activates AhR, upregulating downstream genes associated with pathological left ventricular hypertrophy and fibrosis induced by pressure overload in cardiac myocytes and fibroblasts." (PMID 38883986, 2024). "This study revealed that in the context of CKD, both indoxyl sulphate and the extracellular matrix protein thrombospondin-1 (TSP1) promote features of left ventricular hypertrophy (LVH) through the activation of the aryl hydrocarbon receptor (AhR)." (PMID 38473905, 2024). "Additionally, in cardiac remodeling, KYN-mediated AhR activation exacerbates pathological left ventricular hypertrophy and fibrosis." (PMID 38883986, 2024).